RBP4 (retinol binding protein 4)
Diseases named in the same sentence as RBP4 in open-access papers (continued):
Sharing a sentence is not in itself a finding about the gene and the disease.
Insulin resistance (continued). "Furthermore, baseline RBP4 levels were able to predict hyperglycemia, elevated triglyceride levels, elevated blood pressure, and insulin resistance in the study." (PMID 37510153, 2023). "The effect of RBP4 on arterial elasticity may be partly attributed to itsinduction of insulin resistance in endothelial cells and the reduction ofendothelium-derived NO production." (PMID 39077416, 2023). "Moreover, RBP4, visfatin and chemerin increase systemic inflammation and positively correlated with insulin resistance." (PMID 37576981, 2023). "In addition, other papers published higher serum RBP4 levels in obesity, insulin resistance, type 2 diabetes, metabolic syndrome and in patients with cardiovascular disease." (PMID 36837889, 2023). "While RBP4 appears to be independent of BMI, it has been associated with obesity and insulin resistance." (PMID 37239090, 2023). "Seeing as hyperinsulinemia may be directly associated with hypertension and resulting endothelial dysfunction, the authors speculate that RBP4 could perhaps play a role in the pathophysiology of late-onset PE by inducing insulin resistance in obese women." (PMID 37239090, 2023). "Our findings indicate that 12 weeks of HIFT supplemented with spinach-derived thylakoid reduced levels of leptin, resistin, vaspin, visfatin, apelin, RBP4, chemrin, semaphorin3c and insulin resistance while increasing adiponectin and omentin levels in men with obesity." (PMID 37576981, 2023). "RBP4 is a protein secreted by adipocytes and is a useful biomarker for systemic insulin resistance." (PMID 36364802, 2022). "Retinol-binding protein 4 (RBP4) contributes to insulin resistance in T2DM." (PMID 35807241, 2022). "RBP4 is elevated in insulin resistance and also in diabetes mellitus." (PMID 36499573, 2022). "Fourth, although RBP4 and preeclampsia both pertain to insulin resistance, a limited number of studies have investigated this relationship, so we could not include it in the meta-analysis." (PMID 36558360, 2022). "This could be partially explained by the fact that RBP4 induces the activation of JNK and TLR4 signaling pathways in AT-resident macrophages and thus contributes to AT inflammation-associated insulin resistance." (PMID 35406450, 2022). "Additionally, the adipokine, retinol-binding protein 4 (RBP4), has recently gained attention in its role in peripheral insulin resistance by increasing lipolysis." (PMID 35884888, 2022). "Moreover, transgenic mice overexpressing human RBP4, and mice injected with recombinant RBP4 exhibit insulin resistance, while the genetic deletion of RBP4 enhances insulin sensitivity in mice." (PMID 35406450, 2022). "In addition to insulin resistance, elevated serum or adipose levels of RBP4 are also observed in subjects with morbid obesity and are positively correlated with BMI and markers of macrophages and inflammation." (PMID 35909571, 2022). "The obese diabetic rodents and humans showed increased expression of RBP4 protein, which may provide a link between insulin resistance and obesity." (PMID 35739894, 2022). "Interestingly, proteins related to insulin resistance and inflammation-induced hyperglycemia (retinol-binding protein 4 and haptoglobin, respectively) were downregulated after treatment." (PMID 36364802, 2022). "Therefore, due to its ability to decrease RBP4 serum levels, fenretinide has been evaluated to prevent insulin resistance and glucose tolerance in obese mice and in overweight humans." (PMID 35806431, 2022). "RBP-4 is upregulated in obese rodents and contributes to insulin resistance." (PMID 34893937, 2022). "Transgenic overexpression of human RBP4 in rat was found to induce insulin resistance." (PMID 35082965, 2022). "It has also been reported that RBP4 secreted by the liver and adipose tissue may be involved in insulin resistance, diabetes, and coronary artery disease." (PMID 35745003, 2022).
Insulin resistance (continued). "While decreased levels of RBP4 should be alarming, its continually elevated expression as shown in the present study may be a sign of insulin resistance." (PMID 35977993, 2022). "Moreover, injection of recombinant RBP4 or its transgenic overexpression in mice impaired glucose tolerance and induced insulin resistance." (PMID 36030930, 2022). "This indicates that RBP4 may be related to hyperuricemia through other mechanisms besides insulin resistance." (PMID 35846279, 2022). "Moreover, they found that STAT5 increased TTR expression via hypoxia-inducible factor-1 α, thereby delaying renal clearance and contributing to elevated RBP4 in the circulation and triggering insulin resistance." (PMID 35334893, 2022). "Additionally, the increase in serum RBP4 levels correlated with insulin resistance among the subjects with T2DM, obesity, and impaired glucose tolerance." (PMID 36364802, 2022). "Together, these studies suggest that targeting RBP4 could help in reducing AT inflammation and insulin resistance in patients with obesity and diabetes." (PMID 35909571, 2022). "In addition, the concentration of RBP4 in the blood is associated with cardiovascular risk factors associated with insulin resistance and CHD, circulating RBP4 can be a marker of metabolic complications and atherosclerosis and used to assess CHD." (PMID 36361589, 2022). "Among these, RBP4 is considerably related to insulin resistance." (PMID 36248223, 2022). "Increased transthyretin or alterations in RBP4-transthyretin binding may lead to insulin resistance by stabilizing RBP4 at a higher steady-state concentration in circulation." (PMID 35889910, 2022). "Furthermore, the injection of recombinant RBP4 has been discovered to lead to insulin resistance, whereas genetic deletion of RBP4 enhanced insulin sensitivity." (PMID 35082965, 2022). "According to a prospective longitudinal study including 2,658 participants, higher serum VA level was associated with the progression of NAFLD, which was possibly attributed to increased triglycerides, insulin resistance, serum retinol-binding protein 4, and BMI." (PMID 36172527, 2022). "A recent study showed that RBP4 might be involved in hyperuricemia-induced insulin resistance by inhibiting IRS/PI3K/Akt phosphorylation." (PMID 35846279, 2022). "Importantly, overexpression of RBP4 in mice or its administration elicited insulin resistance and diminished glucose tolerance, whereas RBP4 knockout mice showed improved insulin sensitivity." (PMID 35334893, 2022). "Indeed, HFD-fed RBP4−/− mice exhibit reduced AT inflammation and insulin resistance in comparison to their wild type counterparts." (PMID 35406450, 2022). "The role of RBP4 in the diabetic atherosclerotic process is connected to an increased level of proinflammatory cell surface adhesion molecules, an unfavourable proatherogenic plasma lipoprotein profile, and insulin resistance." (PMID 35082965, 2022). "First elevated RBP4 level impairs insulin cascade signaling in muscle and visceral adipose tissue, contributing to the pathogenesis of insulin resistance, and both the incident obesity and type 2 diabetes were the well-established risk factors for CAD and its severity." (PMID 35369314, 2022). "In agreement with the regulatory role of RBP4 in systemic insulin resistance, mice overexpressing RBP4 displayed severe insulin resistance or glucose intolerance 14, 15, while mice with reduced RBP4 levels exhibited increased insulin sensitivity and improved glucose homeostasis." (PMID 34373742, 2021). "Therefore, a state of hyperinsulinemia, as occurs during insulin resistance, determines an increase in the levels of RBP4." (PMID 34945773, 2021). "The Framingham study showed that RBP-4 was associated with insulin resistance and high blood pressure but not with body mass index." (PMID 34202323, 2021). "These contradictory results implicate that the tissue-specific RBP4 may have distinct roles in the development of insulin resistance." (PMID 34944728, 2021).
Insulin resistance (continued). "RBP4 has been investigated and has a proxy of insulin resistance." (PMID 33544228, 2021). "RBP4 was shown as a marker of insulin resistance, but these results are inconclusive." (PMID 33716957, 2021). "Thus, hepatic GHR overexpression induced systemic insulin resistance through intertissue crosstalk mediated by circulating RBP4." (PMID 34373742, 2021). "RBP-4 has been hypothesized to be a novel adipokine linking adiposity with systemic insulin resistance and potentially with adiposity-related disorders." (PMID 33133591, 2020). "In our study, we found that RBP4 levels in early pregnancy could predict insulin resistance in the second trimester." (PMID 31921323, 2020). "In this study, we found that serum PAI-1, adiponectin, resistin, and RBP4 levels were significant biomarkers for predicting the future progression to prediabetes or type 2 diabetes after adjusting for parameters related to inflammation and insulin resistance." (PMID 31690939, 2020). "However, in adipocytes, RBP4 appears to have a relevant role in obesity and the development of insulin resistance and diabetes." (PMID 32265845, 2020). "Both hepatitis C virus (HCV) infection and retinol-binding protein 4 (RBP4) might contribute to insulin resistance (IR), how RBP4 links to IR in HCV infection remain elusive." (PMID 33135589, 2020). "Previous study reported that the RBP4:retinol ratio and the RBP4:transthyretin ratio might be more informative than RBP4 levels alone when assessing insulin resistance during pregnancy." (PMID 31921323, 2020). "Retinol-binding protein 4 (RBP4) is a recently recognized adipokine, and several epidemiological studies have demonstrated that elevated serum RBP4 concentrations play a critical role in the development of insulin resistance and T2D." (PMID 32178221, 2020). "A study by Kahn BB has first documented the importance of RBP4 in insulin resistance." (PMID 31956345, 2020). "A recent study showed that retinol-binding protein 4 (RBP4) might be an important node that mediates the vicious cycle of insulin resistance and cardiac hypertrophy/heart failure." (PMID 33324685, 2020). "This association between elevated serum RBP4 level and insulin resistance has also been reported in nonobese, nondiabetic people with a strong familial history of type 2 diabetes." (PMID 31690939, 2020). "Thus, the epicardial fat from these patients expresses low levels of glucose transporter, GLUT-4, and high levels of retinol-binding protein 4 (RBP4), associated with insulin resistance." (PMID 32290181, 2020). "Additionally, the overexpression of RBP4 or injection of recombinant RBP4 in wild-type mice leads to the development of insulin resistance." (PMID 31956345, 2020). "Thus, these various effects of elevated level of RBP4 can lead to insulin resistance before any significant changes in diabetic markers in high risk population." (PMID 31953481, 2020). "Firstly, the higher levels of retinol-binding protein 4 and lower levels of adiponectin secreted by adipose tissue, including EAT, prior to 16 GW, could cause insulin resistance (IR), the main mechanisms underlying GDM." (PMID 32306915, 2020). "Further, the LSG brings a decline in RBP4 levels and that may contribute partly to the improved insulin resistance in obese Chinese patients." (PMID 31956345, 2020). "Animal studies showed that injection of RBP4 in normal mice leads to insulin resistance while genetic deletion of RBP4 gene could enhance insulin sensitivity." (PMID 31921323, 2020). "However, new evidence suggests that RBP4 plays a more significant role in the lipid metabolism than in insulin resistance." (PMID 32718041, 2020). "Another pathway of insulin resistance and impaired glucose metabolism may be suggested by high circulating retinol binding protein 4 (RBP4)." (PMID 33076282, 2020). "RBP4 plays an important role in insulin resistance, and the improved glucose metabolism after LSG may be related to RBP4." (PMID 31956345, 2020).
Insulin resistance (continued). "Serum retinol-binding protein 4 (RBP4) plays a critical role in insulin resistance." (PMID 31956345, 2020). "Moreover, in type 2 diabetes mellitus, endothelial dysfunction and insulin resistance often coexist at the earliest stage of atherosclerosis with elevation of serum retinol-binding protein 4 (RBP4), a specific retinol transporter in the blood." (PMID 32156052, 2020). "In contrast to the equivocally reported relationships of circulating RBP4 with obesity, dysglycemia and insulin resistance, positive relationships of RBP4 with total cholesterol, low density lipoprotein (LDL) cholesterol and triglycerides have repeatedly and almost invariably been demonstrated." (PMID 31717719, 2019). "Aberrant expression of RBP4 is linked with development of obesity, NIDDM, and insulin resistance." (PMID 30678306, 2019). "RBP4 is thought be related to obesity, insulin resistance, type-2 diabetes, and metabolic syndrome and is suggested to be an early indicator of the development of insulin resistance and metabolic syndrome, and that this adiponectin is more sensitive to insulin than leptin, IL-6, and CRP." (PMID 30761880, 2019). "The lowering of inflammatory RBP4 levels might be a promising target for the treatment of insulin resistance and obesity-related diseases." (PMID 31208019, 2019). "It is speculated that RBP4 enhances insulin resistance by regulating hepatic TC synthesis and VLDL (Very Low Density Lipoprotein) release into blood, and finally affects fatty acid metabolism." (PMID 31484452, 2019). "Furthermore, RBP4 led to insulin resistance by induction of CD4+ T-helper cell polarization and AT inflammation." (PMID 31208019, 2019). "RBP4 may directly promote adipose tissue inflammation and insulin resistance in humans since enhanced expression of RBP4 in transgenic mice results in adipose tissue inflammation and macrophage accumulation." (PMID 30915034, 2019). "The significant increase in the proinflamatory cytokines TNF-α, IL-6, RBP4, and progranulin, has contributed to promoting insulin resistance and triggering the inflammatory response, resulting in activation of HSCs to produce collagen and stimulate liver fibrosis." (PMID 30096951, 2018). "RBP4 has also been found to affect the insulin signaling cascade, leading to insulin resistance." (PMID 29747616, 2018). "The objective of the present study was to investigate whether RBP4 and TTR are associated with insulin resistance, prediabetes and triglyceride levels in rural Thais with high T2DM risk." (PMID 29747616, 2018). "It has been shown that retinol binding protein 4 (RBP4) is one of the adipokines that participates in the development of insulin resistance by impairing insulin signalling at both the receptor and post-receptor levels, as well as by stimulation of liver gluconeogenesis." (PMID 29524177, 2018). "While our findings need to be explored in the context of human adipose tissue, this study reveals a potential new molecular mechanism that may contribute locally to the dysregulation of RBP4 that occurs in obesity and insulin resistance." (PMID 29114012, 2018). "Our findings indicated that RBP4 and TTR are related to hypertriglyceridemia and insulin resistance; therefore, these markers may involve the risk of heart disease and stroke." (PMID 29747616, 2018). "However, to the best of our knowledge, this is the first report about the potential effect of P. niruri to reduce RBP4 as an effective pathway to prevent steatosis and reduce insulin resistance." (PMID 30096951, 2018). "In addition, we also examined the diagnostic potential of resistin/MCP-1, resistin/RBP4, visfatin/MCP-1, visfatin/SFRP5 and MCP-1/RBP4 indexes in insulin resistance/sensitivity and β-cell function." (PMID 29785210, 2018). "Furthermore, ROC curve analyses demonstrate the diagnostic potential of resistin/RBP4 and MCP-1/RBP4 indexes for T2DM and β-cell function while leptin/MCP-1 index is an additional indicator for insulin resistance/sensitivity." (PMID 29785210, 2018).
Insulin resistance (continued). "RBP4 serum levels have a potential to be an indicator of insulin resistance and decreasing the RBP4 serum levels may be considered as one of the strategies for anti-diabetic therapies of overweight-related T2DM." (PMID 29785210, 2018). "The associations of RBP4 and TTR with hypertriglyceridemia and insulin resistance may have important implications for the risk of heart disease and stroke." (PMID 29747616, 2018). "This might result from specific assay characteristics and/or intrinsic characteristics of RBP4 present in insulin resistance such as altered RBP4·TTR interactions or C-terminal RBP4 proteolysis." (PMID 29416053, 2018). "Recombinant RBP4 administration induced insulin resistance in mice." (PMID 29114012, 2018). "This suggests that RBP4 might play an important role in the disturbance of lipid synthesis in the liver, related to insulin resistance, and perhaps is a surrogate marker of liver steatosis." (PMID 29524177, 2018). "On the other hand, since RBP-4 is secreted by both the liver and WAT, the decreased mass of WAT in bGH mice may account for the decreased levels of RBP-4 found in these animals, suggesting that RBP-4 is associated more with obesity than insulin resistance." (PMID 28670222, 2017). "RBP4 has been speculated to be involved in inflammation and insulin resistance in obesity and type 2 diabetes, but the exact role and regulation in obesity is so far unclear." (PMID 28303117, 2017). "We wanted to investigate whether there is a relationship between circulating irisin, retinol binding protein-4 (RBP-4), adiponectin and proinflammatory mediators implicated in the development of insulin resistance (IR) in metabolic syndrome (MetS)." (PMID 28977161, 2017). "Cohort size, the choice of methodology for the evaluation of insulin resistance, selection bias or methodological differences in RBP4 measurements could contribute to obscure this relatively small impact on IR observed." (PMID 27473078, 2017). "Fenretinide reduces circulating RBP4 levels, but the key importance of this effect in the therapeutic action of fenretinide is controversial, as it also prevents and/or reverses obesity, insulin resistance, and hepatic steatosis in Rbp4 knockout mice on HFD." (PMID 29286303, 2017). "Higher circulating RBP4 levels are associated, independent of insulin resistance and diabetes mellitus, with the risk of colon adenoma." (PMID 28002423, 2016). "The negative result of first-trimester subgroup reveals that with the insulin resistance level increasing during pregnancy, the magnitude of the effect of RBP4 may change." (PMID 26975349, 2016). "The elevated RBP4 was reported in chronic kidney disease and may contribute to insulin resistance in spontaneously hypertensive rats." (PMID 26821914, 2016). "A multi-center clinical study revealed that serum RBP4 levels correlated with the magnitude of insulin resistance in subjects with obesity, impaired glucose tolerance, or type 2 diabetes and in nonobese, nondiabetic subjects with a strong family history of type 2 diabetes." (PMID 26975349, 2016). "The possible effects of reduced RBP4 levels on insulin resistance among CLD patients might warrant further study." (PMID 26927700, 2016). "RBP-4 does not appear to have been investigated in large cohort studies but raised levels are associated with the development of insulin resistance in mice and with obesity and type 2 diabetes in human populations." (PMID 26298350, 2015). "The involvement of RBP4 in insulin resistance has been described in some studies." (PMID 25923078, 2015). "Furthermore, a very recent study determines the mechanism by which RBP4 induces insulin resistance through activation of the antigen presenting cells (APC) of the adipose tissue." (PMID 25923078, 2015). "In addition, the RBP4/retinol complex stimulates JAK2/STAT5 signaling and expression of the suppressor of cytokine signaling 3, which is implicated in insulin resistance." (PMID 25479076, 2014).